MALAT1 (metastasis associated lung adenocarcinoma transcript 1)
Diseases named in the same sentence as MALAT1 in open-access papers (continued):
Sharing a sentence is not in itself a finding about the gene and the disease.
pneumonia (4 papers, 2020 to 2024). An acute, acute and chronic, or chronic inflammation focally or diffusely affecting the lung parenchyma, caused by an infection in one or both of the lungs (by bacteria, viruses, fungi, or mycoplasma.). "A recent study has assessed the association of MALAT1 levels with survival in elderly patients with severe pneumonia." (PMID 39061025, 2024). "In a noteworthy investigation of severe pneumonia, MALAT1 has a prognostic value in elderly patients." (PMID 34558385, 2021). "In vivo, RNAi packaged with adenovirus (Adv) was nasally transfected into BALB/c mice to silence MALAT1, and an MP-infected mouse pneumonia model was prepared." (PMID 33134293, 2020). "Though some data displayed the association of MALAT1 levels with survival in adult patients with pneumonia, its prognostic value in children has not been identified." (PMID 39061025, 2024). "MALAT1 can affect pneumonia by regulating vascular endothelial growth factor (VEGF), which is an important factor influencing inflammation, airway, and associated pathophysiological changes in pneumonia." (PMID 39061025, 2024). "In pneumonia, MALAT1 modulates the inflammatory response by regulating the NF-κB signaling pathway." (PMID 36419933, 2022). "In an investigation of elderly patients with severe pneumonia, lncRNA MALAT1 may function as a biomarker for the prognosis, which opens up new insights on predicting pneumonia." (PMID 34558385, 2021).
rectal cancer (4 papers, 2017 to 2026). A primary or metastatic malignant neoplasm that affects the rectum. "The expression levels of the onco-lncRNAs, including CCAT1, LOC152578, UCA1, CRNDE, PVT1, MALAT1, XLOC_000303, XLOC_006844, BCAR4, and HOTAIR, were significantly increased in the rectal cancer patients compared to the control group." (PMID 35654932, 2022). "As a result, SNP rs1194338 in the promoter region of MALAT1 was significantly associated with decreased CRC risk, especially in the subgroup of no history of cancer, no habit of alcohol drinking, and rectal cancer." (PMID 29190941, 2017).
unstable angina (4 papers, 2019 to 2025). "The lncRNA metastasis-associated lung adenocarcinoma transcript 1 (MALAT1) is upregulated in patients with unstable angina and protects ECs from ox-LDL-induced endothelial injury, partly by upregulating CXCR2 expression through competitive binding with miR-22-3p." (PMID 39959304, 2025). "In our previous work, we found that the expression of lncRNA MALAT1 and LNC_000226 was significantly increased in peripheral blood mononuclear cells (PBMCs) of unstable angina patients comparing to those of normal coronary artery (NCA) controls." (PMID 39641229, 2024). "Since the expression of MALAT1 and LNC_000226 was significantly increased in PBMCs of patients with unstable angina, it is possible that exosomal MALAT1 and LNC_000226 are derived from PBMCs." (PMID 39641229, 2024). "The results indicated that MALAT1 expression in AMI (n=40) was increased compared with angina (n=20) and normal control (n=20)." (PMID 31227612, 2019). "The relative expression levels of MALAT1 in AMI patients (n=40), normal control (n=20) and angina patient (n=20) were determined by qRT-PCR." (PMID 31227612, 2019).
uterine cancer (4 papers, 2013 to 2025). Primary or metastatic malignant neoplasm involving the uterine corpus and/or the cervix. "Another important gene in the context of uterine carcinoma is the MALAT-1 (metastasis-associated lung adenocarcinoma transcript 1) gene." (PMID 39912983, 2025). "Metastasis-Associated Lung Adenocarcinoma Transcript 1 (MALAT1) is widely expressed in normal human tissues and is upregulated in various human cancers, including breast, prostate, colon, liver, and uterus cancers." (PMID 27660759, 2016).
acute lung injury (3 papers, 2019 to 2022). A condition of lung damage that is characterized by bilateral pulmonary infiltrates (pulmonary edema) rich in neutrophils, and in the absence of clinical heart failure. "MALAT1 was found upregulated and relates to activation of nuclear factor kappa-light-chain-enhancer of activated B cells (NF-κB) signaling in the lipopolysaccharide (LPS)-induced acute lung injury model." (PMID 31871512, 2019).
aortic aneurysm (3 papers, 2018 to 2024). A ruptured aneurysm located in the wall of the proximal portion of the descending aorta proceeding from the arch of the aorta. "MALAT1 is necessary for targeting HDAC9 to the nucleus and depletion of MALAT1 or HDAC9 reverses deleterious cellular phenotypes and modifies VSMC-dependent pathology including inhibiting experimental aortic aneurysm." (PMID 29520069, 2018).
B-cell neoplasm (3 papers, 2022 to 2024). A group of heterogeneous lymphoid tumors generally expressing one or more B-cell antigens or representing malignant transformations of B-lymphocytes. "We also studied the potential causes and consequences of MALAT1 upregulation that might justify its clinical behavior in indolent B cell neoplasms." (PMID 37803049, 2023). "In this report, we provide novel insights into the clinical and biological role of MALAT1 in indolent B cell neoplasms." (PMID 37803049, 2023). "In summary, these findings highlight that MALAT1 overexpression plays a role in the pathobiology and clinical behavior of indolent B cell neoplasms related to a more aggressive behavior of the tumors with higher MALAT1 levels." (PMID 37803049, 2023). "MALAT1 long non-coding RNA has oncogenic roles but has been poorly studied in indolent B-cell neoplasms." (PMID 37803049, 2023). "In summary, MALAT1 expression is related to pathophysiology and more aggressive clinical behavior of indolent B-cell neoplasms." (PMID 37803049, 2023). "While functions of the majority of identified lncRNA are poorly studied, some of them (e.g., NEAT1 and MALAT1) play a role in development of B-cell neoplasms." (PMID 36275462, 2022).
brain injury (3 papers, 2018 to 2025). Acute and chronic (see also brain INJURIES, CHRONIC) injuries to the brain, including the cerebral hemispheres, CEREBELLUM, and brain STEM. "This becomes even more important because it has been shown that MALAT-1 actually mediates inflammation in traumatic brain injury." (PMID 31231228, 2019).
Cachexia (3 papers, 2021 to 2025). Severe weight loss, wasting of muscle, loss of appetite, and general debility related to a chronic disease. "Moreover, MALAT1 was weakly expressed in the subcutaneous white adipose tissue of cancer-associated cachexia patients and was related to low fat mass index and poor prognosis in cancer patients." (PMID 33691715, 2021). "Various studies, and especially, have found that MALAT1 is mainly localized in the nucleus, and in patients with cancer-related cachexia, MALAT1 is downregulated in white adipose tissue (WAT) nuclei, which is associated with a low fat mass and a poor prognosis for cancer." (PMID 38674413, 2024). "Additionally, MALAT1 has been associated with a low fat mass index (FMI) and poor prognosis in cancer patients, and it is underexpressed in the subcutaneous white adipose tissue of individuals with cancer-related cachexia." (PMID 40150019, 2025). "This study indicated that MALAT1 is associated with adipose loss in cancer-associated cachexia by regulating adipogenesis through PPAR-γ, which may potentially be a novel target for the diagnosis and treatment of cancer-associated cachexia in the clinic." (PMID 33691715, 2021).
cartilage disease (3 papers, 2022 to 2025). Softening and degeneration of the CARTILAGE. "Recently, MALAT1 has been reported to be associated with the development of bone and cartilage diseases by orchestrating the signaling network." (PMID 36452326, 2022). "Previous studies have demonstrated the role of the lncRNA Malat1 in bone and cartilage diseases and osteogenic differentiation." (PMID 40503910, 2025). "Metastasis-associated lung adenocarcinoma transcript-1(MALAT1) is a highly conserved lncRNA that is closely associated with the initiation and development of bone and cartilage diseases." (PMID 38672411, 2024). "The interactions between MALAT1/protein and MALAT1/RNA are the essential ways for MALAT1 to regulate the activity in bone and cartilage diseases, including OP, OA, IDD, RA, JIA, AS, and GA." (PMID 36452326, 2022). "MALAT1, a well-studied lncRNA, plays a key role in bone and cartilage diseases by regulating the biological processes of osteogenic differentiation, proliferation, and apoptosis." (PMID 36452326, 2022). "Although the potential mechanisms of MALAT1 in mediating the cellular processes of bone and cartilage diseases are still needed for further elucidation, MALAT1 shows great promise for drug development." (PMID 36452326, 2022). "The involvement of MALAT1 in the pathological development of bone and cartilage diseases makes it available to be a potential biomarker for clinical diagnosis or prognosis." (PMID 36452326, 2022). "However, the molecular mechanisms of MALAT1 in regulating the pathogenesis and progression of bone and cartilage diseases remain largely unclear." (PMID 36452326, 2022).
chronic kidney disease (3 papers, 2021 to 2025). Impairment of the renal function secondary to chronic kidney damage persisting for three or more months. "Bijkerk and colleagues show that pharmacological intervention of the lncRNA Malat1 protected against fibrosis in experimental kidney injury and preserved vascular integrity and may serve as potential treatment for chronic kidney disease." (PMID 40978530, 2025).
colorectal tumor (3 papers, 2021). "Mechanistically, KDM4C overexpression in colorectal tumor tissues and metastatic samples can lower H3K36me3 and H3K9me3 levels at MALAT1 promotors, thereby upregulating MALAT1 expression and enhancing β-catenin signaling pathway strength, conferring tremendous metastatic potential for CRC cells." (PMID 34715919, 2021). "We further compared the expression levels of HOTAIR, MALAT1 and LOC285194 in primary colorectal tumors at the time of initial diagnosis and correlated them with disease progression and liver metastasis." (PMID 34307387, 2021).
cutaneous squamous cell carcinoma (3 papers, 2019 to 2024). "Moreover, in skin, the lncRNA MALAT1 was shown to interact with the transcription factor MYC and bind to the promoter region of the Kinectin 1 (KTN1) gene, thus contributing to enhancement of epidermal growth factor (EGF) signaling in cutaneous squamous cell carcinoma." (PMID 38542324, 2024).
diabetic neuropathy (3 papers, 2022). A chronic, pathological complication associated with diabetes mellitus, where nerve damages are incurred due to diabetic microvascular injury involving small blood vessels that supply these nerves, resulting in peripheral and/or autonomic nerve dysfunction. "LncRNA MALAT1 was significantly upregulated in the peripheral-blood mononuclear cells of patients with diabetic neuropathy." (PMID 36297381, 2022). "Therefore, the study suggests a possible involvement of the MALAT1/CXCR4 axis in the pathogenesis of diabetic neuropathy." (PMID 36297381, 2022). "MALAT1 expression was increased in the diabetic neuropathy group when compared to the non-diabetic neuropathy and healthy controls groups." (PMID 36555704, 2022).
hyperlipidemia (3 papers, 2020 to 2023). "Interestingly, mice treated with exosomes secreted by Ox-LDL-treated human umbilical vein endothelial cells lead to hyperlipidemia, local inflammation, and the formation and worsening of AS plaques by upregulating the expression of metastasis-associated lung adenocarcinoma transcript 1 (MALAT1)." (PMID 38132306, 2023).
Infertility (3 papers, 2022 to 2025). "Similarly, MALAT1 in semen has been correlated with sperm quality parameters in infertile men54." (PMID 40425698, 2025). "We investigated the seminal plasma and serum expression profiles of TUG1, MALAT1, miR-483, and miR-141 and their targets TGF-β1 and STAT3 in severe male factor infertility." (PMID 40425698, 2025). "MSTRG.13411.12 and MSTRG.13411.14 are near MALAT1 locus, suggesting that MALAT1 is involved in the pathological regulation of GCs from OEM-related infertility patients." (PMID 35295989, 2022). "In this context, this study aimed to investigate the seminal plasma and serum expression of TUG1, MALAT1, miR-483, and miR-141 and their networks TGF-β1 and STAT3 in infertile men with non-obstructive azoospermia (NOA) and severe oligozoospermia (SO)." (PMID 40425698, 2025).
infiltrating ductal carcinoma (3 papers, 2019 to 2021). "PNPO could be regulated by the MALAT1/miR-216b-5p/PNPO axis in the development of human breast invasive ductal carcinoma." (PMID 35127701, 2021). "A negative correlation between overall survival and the expression of MALAT1 was statistically significant in the group of diagnosis age below 60 or in the group of infiltrating ductal carcinoma analyzed by TCGA database, which declared that MALAT1 might be a potentially useful prognostic factor." (PMID 30683807, 2019). "Interestingly, for the group of diagnosis age below 60 or infiltrating ductal carcinoma, we found that a correlation between an improved survival with MALAT1 low expression was statistically significant and MALAT1 was an independent prognostic factor among them." (PMID 30683807, 2019).
kidney cancer (3 papers, 2022 to 2025). Primary or metastatic malignant neoplasm involving the kidney. "For example, KCQN1OT1 and MALAT-1 are the kidney cancer-associated onco-lncRNAs, and H19 and GAS5 are the kidney cancer-associated tumor suppressive lncRNAs." (PMID 34983363, 2022). "Urinary exosomes from 30 Wilms’ tumor patients with a rare kidney cancer and 27 healthy controls were collected and quantified by qPCR for metastasis-associated lung adenocarcinoma transcript-1 (MALAT1), showing that MALAT1 expression was decreased in Wilms’ tumor patients." (PMID 40075875, 2025).
laryngeal squamous cell carcinoma (3 papers, 2020). A squamous cell carcinoma that arises from the larynx. "This study was aimed to evaluate the involvement of lncRNA MALAT1 in modifying chemo‐sensitivity of laryngeal squamous cell carcinoma (LSCC) cell lines." (PMID 31837057, 2020). "Down-regulation of MALAT1 expression can also inhibit the migration and invasion of laryngeal squamous cell carcinoma cell (Hep-2) and hypopharyngeal cancer cell (FaDu)." (PMID 31792655, 2020).
liver failure (3 papers, 2019 to 2025). A liver disease characterized by the liver losing or has lost all of its function. "A low expression level of MALAT1 was associated with more than a 5-fold higher probability of anemia (OR = 5.36; p = 0.040) and over a 6-fold higher chance of liver failure (OR = 6.07; p = 0.037) after the completion of RT." (PMID 40150019, 2025). "In contrast, our study revealed that HCC smokers with the MALAT1 rs1194338 polymorphism (CA + AA) had a lower risk of developing moderate to severe liver failure." (PMID 31500187, 2019). "We found that smokers with the MALAT1 rs1194338 polymorphism (CA + AA) had a lower risk of developing moderate to severe liver failure (Child–Pugh B or C grade)." (PMID 31500187, 2019). "We speculated that tobacco carcinogens might alter MALAT1 expression dependent upon the presence of the rs1194338 and rs3200401 polymorphisms and further influence the severity of liver failure and frequency of HBV infection in HCC patients." (PMID 31500187, 2019). "Our study demonstrates that both low MALAT1 and NEAT1 expression levels are significantly associated with a higher probability of post-RT adverse effects, including anemia, liver failure, and nutritional deficiencies." (PMID 40150019, 2025). "Our results are consistent with these findings, as we observed a higher frequency of anemia and liver failure in patients with a lower expression not only of MALAT1 but also of NEAT1." (PMID 40150019, 2025). "Additionally, patients with liver failure had a significantly lower expression of both MALAT1 (median: 0.32 vs. 0.47; p = 0.013) and NEAT1 (median: 0.32 vs. 0.44; p = 0.026)." (PMID 40150019, 2025). "LC patients with poor performance status (ECOG) (OR = 4.62; p = 0.047), as well as lower MALAT1 expression (OR = 1.49; p = 0.015) and NEAT1 expression (OR = 9.09; p = 0.005), had a significantly greater likelihood of liver failure." (PMID 40150019, 2025).
neonatal respiratory distress syndrome (3 papers, 2020 to 2022). "Similar to our findings, MALAT1 has been shown to be significantly increased in the peripheral blood mononuclear cells with infection exposure and treated with LPS in neonatal respiratory distress syndrome." (PMID 32315984, 2020).
peripheral nerve injury (3 papers, 2021 to 2024). Injury to a peripheral nerve. "A previous study indicated that long-chain non-coding RNA MALAT1 was enhanced after peripheral nerve injury, which increased the expression and secretion of BDNF through sponging miR-129-5p, thus promoting proliferation and migration of Schwann cells." (PMID 35012663, 2022). "MALAT1 is involved in synaptic density, Schwann cell proliferation and migration, and in initiating regenerative responses after peripheral nerve injury." (PMID 34621163, 2021).
polycystic ovary syndrome (3 papers, 2021 to 2024). A disorder that manifests as multiple cysts on the ovaries. "In the reproductive system, MALAT1 was shown to be associated with pregnancy loss, polycystic ovary syndrome (PCOS), and endometriosis." (PMID 33681369, 2021). "In polycystic ovary syndrome (PCOS), lncRNA MALAT1 reduction could suppress TGFβ signaling through sponging miR-125b and miR-203a in granulosa cells." (PMID 35812382, 2022).
prostate adenocarcinoma (3 papers, 2021 to 2025). "Additionally, elevated MALAT1 expression was associated with a significant decrease in disease-free survival in COAD, Liver Hepatocellular Carcinoma (LIHC), and Prostate Adenocarcinoma (PRAD)." (PMID 40597438, 2025).